DCK (deoxycytidine kinase)
Diseases named in the same sentence as DCK in open-access papers (continued):
Sharing a sentence is not in itself a finding about the gene and the disease.
tumor (continued). "Deoxycytidine kinase (dCK) is a key enzyme in deoxyribonucleoside salvage and the anti-tumor activity for many nucleoside analogs." (PMID 27879648, 2016). "After being phosphorylated by DCK (deoxycytidine kinase) to its active form, it finally exerts its anti-tumor growth properties." (PMID 26176887, 2015). "An increase in dCK levels in human tumor cells was demonstrated for the first time in response to combined treatment with TK2 siRNA and gemcitabine (but neither treatment alone)." (PMID 26087398, 2015). "Future work will be aimed at determining specific tumor types which exhibit robust dCK activation and [18F]-FAC accumulation after IR." (PMID 25101980, 2014). "Nevertheless, the G12 mutant has an effect also on tumour cells presenting an endogenous dCK activity, like HT29 and HEK-293T." (PMID 22927829, 2012). "Accordingly, there is a direct correlation between the level of dCK expression and the sensitivity to deoxycytidine analogues in different types of tumor." (PMID 22927829, 2012). "The application of the Retrovolution system led to the identification of a dCK mutant that fulfils the long-sought feature of increasing sensitivity of tumour cells to Gemcitabine treatment, based on the presence of mutations unpredictable on a rational basis." (PMID 22927829, 2012). "In the present study, the relation between deoxycytidine kinase (dCK) activity and the radiosensitising effect of gemcitabine was investigated in eight different human tumour cell lines." (PMID 16734894, 2006). "Oral IACS-010759 administration significantly inhibited DCK-KO tumor growth in a xenograft model." (PMID 38346958, 2024). "Moreover, we observed a significantly higher expression of CDA and a trend towards higher expression of DCK in human tumor samples in comparison to the surrounding stroma." (PMID 38744194, 2024). "In tumor cell lines, low expression of deoxycytidine kinase is associated with decitabine resistance but does not affect the metabolism of azacitidine." (PMID 39415836, 2024). "The major mechanisms of the action of gemcitabine are abrogating DNA synthesis and self-potentiation by activating deoxycytidine kinase and caspase signaling, leading to apoptosis, which has modified tumor microenvironment and ultimately influenced the APT signal." (PMID 38258112, 2024). "DCK is a rate-limiting enzyme of the salvage pathway, which is involved in the synthesis of deoxyribonucleotide triphosphates (dNTPs); dNTPs are essential for DNA replication, repair, and tumor growth." (PMID 35804923, 2022). "The pharmacokinetics of gemcitabine in tumor cells is regulated by human equilibrative nucleoside transporters (hENTs)-mediated uptake, activation by deoxycytidine kinase (DCK), and inactivation by cytidine deaminase (CDA), deoxycytidylate deaminase (DCTD), and cytosolic 5′-nucleotidases (NT5C1A)." (PMID 33546284, 2021). "Negative association between DCK and tumor purity suggested that DCK expression was from cells in the tumor environment." (PMID 32690026, 2020). "Moreover, DCK expression was positively correlated with TIICs, including CD4+ and CD8+ T cells, B cells, monocytes, tumor-associated macrophages (TAMs), M1 and M2 macrophages, neutrophils, natural killer cells, and dendritic cells." (PMID 32690026, 2020). "It was confirmed that ABCG2 inhibitors would effectively increase the anti-tumor efficacy of purine nucleosides by blocking drug efflux which may be a significant of resistance when dCK levels are low22." (PMID 31575977, 2019). "We also performed IHC to determine the expression of dCK in the xenograft tumor tissue sections." (PMID 31842285, 2019). "While we find low DCK expression in tumour biopsies from patients treated with gemcitabine, assessed by immunostaining and image analysis, correlates with a poor prognosis, we find no such correlation in tumour biopsies from a Phase I cohort treated with NUC-1031." (PMID 31113993, 2019).
tumor (continued). "In addition, after co-administration of DBD with GEM, Western Blot and qPCR results confirmed that the expression of deoxycytidine kinase (dCK) in tumor tissues of LLC-bearing mice were markedly increased." (PMID 31130654, 2019). "Therefore, we think it is appropriate to avoid referring to these cells as tumor cells instead of dCK+ cells." (PMID 31307406, 2019). "Low deoxycytidine kinase expression in tumour biopsies from patients treated with gemcitabine, assessed by immunostaining and image analysis, correlates with a poor prognosis, but there is no such correlation in tumour biopsies from a Phase I cohort treated with NUC-1031." (PMID 31113993, 2019). "The anti-tumour effect of masitinib/gemcitabine combination treatment was also investigated in CHO cells (constitutive dCK), CHO dCK- cells (deficient dCK), and CHO dCK Rescue cells (partially reconstituted dCK)." (PMID 29127277, 2017). "Using [18F]-FAC, a dCK-specific positron emission tomography (PET) probe, we visualized and quantified dCK activation in tumor xenografts after IR, indicating that dCK activation could serve as a biomarker for ATM function and DNA damage response in vivo." (PMID 25101980, 2014). "Recent advances in our understanding of the structure and function of deoxycytidine kinase (dCK), a critical enzyme required for the anti-tumor activity for many nucleoside analogs, have clarified the mechanistic role this kinase plays in chemo- and radio-sensitization." (PMID 24066967, 2013). "Thus, the effects of Dec are likely tissue specific, as DCK is selectively expressed in tumor cells and myeloid cells, thus protecting T and B cells from the potentially deleterious demethylating effects of this agent." (PMID 23097673, 2012). "Our results further imply that, in addition to the dATP increase by dCK activation in tumor cells, dCK may also involve in the apoptotic regulation." (PMID 23300702, 2012). "Furthermore, we observed that DCK expression was relevant to the expression of markers of T cell subsets, like Th1, Th2, Tfh, and Th17, indicating its potential influence on the tumor progression in regulating the secretion of cytokines from the helper T cells." (PMID 32690026, 2020). "However, whether DCK could influence immune cell and tumor microenvironment contributing to tumor progression still need investigation." (PMID 32690026, 2020). "Indeed, preclinical studies have also shown that pretreatment dCK expression level could be used as a predictive parameter of tumour sensitivity and a clear correlation between dCK activity and gemcitabine sensitivity was observed in several tumour xenografts." (PMID 16868547, 2006). "CYL-02 utilizes plasmid DNA containing genes for somatostatin receptor 2 (SSTR2), deoxycytidine kinase (DCK), and uridylate monophosphate kinase (UMK), which together aim to restore gene function in PDAC cells while also sensitizing the tumor to gemcitabine." (PMID 39518005, 2024). "In summary, our study unveils a new intracellular metabolic pathway of 5hmdC and 5fdC reliant on DCK and DCTD, which mediates the anti-tumor effects and expands the therapeutic potential of these compounds." (PMID 37378658, 2023). "Therefore, inhibiting the activity of DCK may inhibit tumor growth." (PMID 35804923, 2022). "Phosphoproteomics and RNA-Seq analyses identified a strong E2F response in treated cells and tumours, as well as key targets of ATR activity in response to replication stress in NB cells (including FANCD2, FANCI, ATRX and DCK)." (PMID 34819497, 2021). "We found that the DCK expression was significantly correlated with the expression of gene markers in monocytes, TAM, and M2 macrophages in HCC patients after adjusting tumor purity." (PMID 32690026, 2020).
tumor (continued). "Interestingly, the expression of DCK was associated with the gene markers like CCR8, STAT5b, and TGFB1 of Tregs, and PD–1, CTLA–4, LAG3, TIM–3, and GZMB of exhausted T cells after adjusting tumor purity, revealing that increased expression of DCK was associated with immunosuppression in HCC." (PMID 32690026, 2020). "The expression of DCK in HCC was analyzed through the Oncomine and Tumor Immune Estimation Resource (TIMER) databases." (PMID 32690026, 2020). "Therefore, differentially expressed DCK in tumor tissues could influence the immune cell functions." (PMID 32690026, 2020). "Lastly, the wet-lab qRT-PCR experiments compared the mRNA expressions of PPAT, ATIC, IMPDH1, DCK, and RRM2 in between 10 pairs of human primary HCC tissues and neighboring non-tumor liver tissues." (PMID 33520699, 2020). "The decreased tumor sizes and low Ki-67 expression in tumor xenograft models further indicated that DDB1 regulates GEM metabolism by affecting dCK, which expands the size of the dNTP pools." (PMID 31842285, 2019). "The DCK::UMK (deoxycitine kinase::uridyl monophosphate kinase) fusion gene, by phosphorylating twice intracellular gemcitabine, also induced a significant tumor regression and bystander effect in our relevant models of PDAC." (PMID 28594388, 2017). "We identified SSTR2 and DCK::UMK as complementary therapeutic genes to sensitize cancer cells to chemotherapy, to induce tumor regression and to block metastatic dissemination in experimental models." (PMID 28594388, 2017). "dCK triggers the phosphorylation of cytarabine (Ara-C), CNDAC and other nucleoside analog drugs, which then inhibit tumor growth and promote apoptosis." (PMID 27879648, 2016). "Moreover, pretreatment dCK expression level could be used as a predictive parameter of tumor sensitivity, as observed with a clear correlation between dCK activity and gemcitabine sensitivity in tumor cells and xenografts." (PMID 27007129, 2016). "Taking the [18F]-FAC accumulation in 10K tumor as a background signal, IR induced a forty percent increase in [18F]-FAC accumulation in tumors expressing WT dCK." (PMID 25101980, 2014). "Based on the importance of the biomarkers involved in gemcitabine metabolism, we assessed the expressions of three key molecules (hENT1, dCK, and RRM1) in tumor samples from 28 patients with advanced BTC who received first-line gemcitabine monotherapy." (PMID 23710668, 2013). "Moreover, even though dCK is thought to participate in the salvage pathway of DNA synthesis, the present results further imply that dCK could play more complicated roles through interacting with other proteins or signaling pathways in the apoptotic process of tumor cells." (PMID 23300702, 2012). "Decitabine is a particularly attractive option to induce CTA expression as it functions as a prodrug which requires activation by deoxycytidine kinase (DCK), an enzyme preferentially expressed in tumor cells and myeloid cells." (PMID 23097673, 2012). "DCK and UCK2 in four model genes were highly expressed in the response group which referred to potentially serve as a predictive factor related to the response of tumor immune therapy." (PMID 38517376, 2024). "As the abundance of DCK determines the tumor killing effect of oxidized methylcytidines in a DCTD-dependent manner, expression analysis of components of the DCK-DCTD axis in patients would provide a useful biomarker in cancer therapeutic applications of 5hmdC and 5fdC." (PMID 37378658, 2023). "We then asked whether knockdown of other nucleotide kinases (such as deoxycytidine kinase, DCK) results in increased DNA damage and determined if this knockdown affects LUAD tumor forming ability in vitro." (PMID 31589613, 2019). "The dCK activity was 1.55 nmol/hour/μg of total protein for liver tissue, while HCC extracts showed 4.38 and 4.68 nmol/hour/μg of total protein dCK activity for tumor samples." (PMID 31703407, 2019).
tumor (continued). "Therefore, the regulation of dCK and P-gp played important roles in the alternation of GEM pharmacokinetics and the enhancement of the anti-tumor effect of GEM." (PMID 31130654, 2019). "In tumor cells, for instance, gemcitabine-metabolizing enzyme levels and activity such as CDA, dCK or Nt5c1A/Nt5c3 may explain the discrepancy between high hENT1 level and poor response to gemcitabine." (PMID 31752123, 2019). "For example, using gemcitabine treatment in tumours of different origin such as pancreas and lung, it was shown that resistance only is predicted by dCK activity and protein level, and not by dCK mRNA level, in agreement with our data." (PMID 29695239, 2018). "mRNA levels of hENT1, CHOP, MRP1 and DCK were evaluated by means of qRT-PCR in matched pairs of tumor and adjacent normal tissue samples collected from PDAC patients treated with gemcitabine after surgical tumor resection." (PMID 25199538, 2014). "Thus, the DCK and EPO from IRGs may regulate the expression of some specific immune checkpoints and promote the tumor escape mechanisms in HCC." (PMID 34021184, 2021). "We next assessed whether the phenotype of the gemR models acquired in vivo differed from drug-sensitive counterparts with respect to expression of proteins involved in gemcitabine transport into tumor cells (hCNT1 and hENT1) or in gemcitabine metabolism (RRM1, RRM2, CDA, dCK)." (PMID 33073205, 2020). "However, the expression of DCK was not correlated with tumor purity (cor = 0.024, p = 6.58 × 10− 1), suggesting the expression of DCK was from cells in the tumor microenvironment." (PMID 32690026, 2020). "Our findings demonstrate that SC is a potent anti-tumor agent that not only reduces proliferation and induces apoptosis in resistant cells, but may also enhance the effectiveness of cytarabine by increasing the expression of ENT1 (equilibrium nucleoside transporter 1) and dCK (deoxycytidine kinase)." (PMID 39339789, 2024). "In addition, DCK upregulation in tumor cells may indicate a minimized 5hmdC toxicity for normal tissues in which DCK expression is relatively low, consistent with the lack of discernible adverse effects on cord blood-derived CD34+ cells and in mice administered with 5hmdC." (PMID 37378658, 2023). "However, knockdown of DCK failed to inhibit LUAD tumor growth, indicating that the DNA damage that results from TK1 knockdown is unlikely to play a role in the inhibition of LUAD tumor growth and metastasis." (PMID 31589613, 2019).
cancer (56 papers, 2006 to 2025). A tumor composed of atypical neoplastic, often pleomorphic cells that invade other tissues. "HuR is strongly associated with the DCK mRNA level, and HuR-overexpressing cancer cells have been shown to be more sensitive to gemcitabine treatment." (PMID 35582220, 2020). "Acquired resistance of MCL cells to araC is associated with downregulation of DCK, enzyme of the nucleotide salvage pathway responsible for the first phosphorylation (=activation) of most nucleoside analogs used in anti-cancer therapy." (PMID 24972933, 2014). "Cancer cells deficient in deoxycytidine kinase are very sensitive to the cytotoxic action of 3-deazauridine." (PMID 23369223, 2013). "An alternative approach that merits discussion uses insight gained from structural and functional studies of dCK to guide the design of dCK variants that can be expressed in cancer cells using gene therapy technology." (PMID 24066967, 2013). "These cells constitute a model of tumoral cells acquiring resistance to deoxycytidine analogues due to a loss of dCK activity, a fundamental problem that has to be bypassed for an improvement of cancer treatment." (PMID 22927829, 2012). "In conclusion, these results describe the identification and molecular characterisation of a new variant of the human dCK enzyme that could be of great interest as either a safety gene with utility in cell therapy approaches, or as suicide gene for cancer treatment." (PMID 26485161, 2015). "In resistant cancer cell lines, DCK is downregulated via promoter hypermethylation and thus cannot phosphorylate the nucleoside, resulting in reduced cytotoxicity." (PMID 40723396, 2025). "Deoxycytidine kinase (dCK), a critical enzyme in the activation of gemcitabine, is often downregulated in gemcitabine-resistant cancer cells." (PMID 39757310, 2025). "An example of this is the use of CRISPR to demethylate SLC29A1 and DCK promoter regions, increasing their expression, resulting in resistant cancer cells becoming resensitized to nucleoside analogs." (PMID 40723396, 2025). "Among the 10 phosphopeptides upregulated in the high relapse-risk group, KIAA1522, DCK, FOXO3 and MYO9B are notable for their association with aggressive cancer phenotypes." (PMID 38745208, 2024). "The target responsible for this sensitization is dCK, and we revealed how masitinib, as well as a few other TKis used to treat cancer, such as imatinib, interacts with dCK." (PMID 37248212, 2023). "In human cancer cells, 5hmdCMP and 5fdCMP can be generated by DCK through the phosphorylation of 5hmdC and 5fdC, thus providing potential substrates for DCTD." (PMID 37378658, 2023). "Because dCK is the rate-limiting enzyme of the SP, it is a target of choice for antiproliferative therapies for cancers where the SP is essential or upregulated." (PMID 37248212, 2023). "Deoxycytidine kinase is the rate-limiting enzyme of the salvage pathway and it has recently emerged as a target for antiproliferative therapies for cancers where it is essential." (PMID 37248212, 2023). "After its entry into cancer cells, it is, first of all, phosphorylated by deoxycytidine kinase (dCK) and, subsequently, undergoes a series of phosphorylation steps that transform it into gemcitabine di- and tri-phosphate (dFdCDP and dFdCTP)." (PMID 37835408, 2023). "In cancer cells, hENT1 inhibition significantly downregulated gemcitabine uptake and cytotoxicity, whereas DCK knockdown reduced cytotoxicity." (PMID 33287390, 2020). "The study revealed a novel positive correlation between gemcitabine sensitivity and levels of its active metabolites or protein expression ratios hENT1/CDA and hENT1 × DCK/CDA × DCTD in cancer cells." (PMID 33287390, 2020). "Ara-C is a prodrug that must be transported within the cancer cells, phosphorylated by deoxycytidine-kinase (DCK) and other kinases to cytarabine-tris-phosphate (ara-CTP), and incorporated into DNA, to be able to exert its anti-proliferative activity." (PMID 32197371, 2020).